TRPM7 (transient receptor potential cation channel subfamily M member 7)
Diseases named in the same sentence as TRPM7 in open-access papers (continued):
Sharing a sentence is not in itself a finding about the gene and the disease.
pancreatic cancer (continued). "A previous study had proven that TRPM7 is necessary for pancreatic cancer cell invasion." (PMID 33617107, 2021). "However, this is only descriptive and further experiments are needed to better understand how AG-9 acts with TRPM7 channels to enhance pancreatic cancer cell migration." (PMID 32733880, 2020). "Targeting TRPM7 enhances cytotoxicity of the conventionally used chemotherapeutic, gemcitabine, which is a pro-apoptotic agent, suggesting that targeting TRPM7 in pancreatic cancer could support standard chemotherapy." (PMID 32182937, 2020). "In nasopharyngeal, lung and pancreatic cancer cells, TRPM7 promotes cell migration." (PMID 32887220, 2020). "For example, TRPM7 is upregulated in pre-malignant pancreatic cancer compared to normal pancreatic tissue, and so it could potentially serve as a candidate for a pancreatic cancer biomarker." (PMID 32182937, 2020). "The main TRPM channel involved in pancreatic cancer is TRPM7." (PMID 29875336, 2018). "Our results showing that TRPM7-mediated CSCs-like phenotype in lung cancer is modulated by Hsp90α/uPA/MMP2 signaling is therapeutically-relevant and partially consistent with recently demonstrated role of TRPM7 in the regulation of pancreatic cancer cell invasion through the Hsp90α/uPA/MMP2 pathway." (PMID 30477473, 2018). "Besides pancreatic cancer, TRPM7 is required for proliferation of cancer cells derived from a variety of malignant tumors." (PMID 28379203, 2017). "In pancreatic cancer cells, small interfering RNA (siRNA)-induced knockdown of TRPM7 induced cell death without causing apoptosis." (PMID 28379203, 2017). "However, the clinicopathological significance of TRPM7 in pancreatic neoplasms and the functional roles of TRPM7 in pancreatic cancer remain to be explored." (PMID 25770184, 2015). "Continued research to understand the biology of TRPM7 channels will have important implications for exploitation of TRPM7 as biomarkers and targets with the hope of producing a positive impact towards personalized therapy and prevention of pancreatic cancer." (PMID 25770184, 2015). "Based on these observations, we hypothesize that the TRPM7 channels regulate cellular fluxes of Mg2+ and modulate mitogen-induced signaling, which mediate its control of growth and invasion in pancreatic cancer." (PMID 25770184, 2015). "The results demonstrate that TRPM7 channels are over-expressed in a proportion of the pre-malignant lesions and malignant tumors of the pancreas, and they are necessary for invasion by pancreatic cancer cells." (PMID 25770184, 2015). "However, the biological significance of TRPM7 channels in pancreatic neoplasms was mostly unexplored." (PMID 25770184, 2015). "We propose that TRPM7 channels play important roles in development and progression of pancreatic neoplasm, and they may be explored as clinical biomarkers and targets for its prevention and treatment." (PMID 25770184, 2015). "This important point can be illustrated by TRPM7 in pancreatic cancer." (PMID 25079291, 2014). "In particular, the analysis of the TRPM7 interactome using experimental data (BioGRID) and modeling tools (ProteinPrompt) has allowed us to isolate 19 genes of interest mainly related to small GTPase pathways involved in digestive neoplasia such as colorectal and pancreatic cancers." (PMID 41395111, 2025). "Since TRPM7 expression has a direct impact on the activation process of the PSCs, TRPM7 channel is of utmost importance in these cells and future studies will help define the role of TRPM7 modulation in in vivo experiments and as a potential target in pancreatic cancer." (PMID 35883700, 2022). "Additionally, downregulation of TRPM7 in human pancreatic cancer cells led to inhibition of proliferation by arresting the cells in the G0/G1 and G2/M phases of the cell cycle; these effects could be reversed by Mg2+ supplementation." (PMID 28379203, 2017).
pancreatic cancer (continued). "Furthermore, TRPM7 might regulate exocrine pancreatic development, and aberrant TRPM7-mediated signaling contributes to the development of pancreatic cancer." (PMID 27835598, 2016). "Whether TRPM7 channels are required for pancreatic cancer cell invasion remains to be explored." (PMID 25770184, 2015). "Besides, our current studies using human pancreatic adenocarcinoma cells provide novel evidence that silenced expression of TRPM7 impedes cell migration (Yee NS, unpublished data), suggesting TRPM7 plays an important role in invasion and metastasis of pancreatic cancer." (PMID 24278689, 2012). "We investigated the expression of TRPM7, TRPM6 and POSTN in pancreatic cancer samples (PAAD-TCGA) and normal pancreas samples from GTEX using GEPIA2021, which enables to filter the cell types of interest in normal tissue from GTEX or cancer types from TCGA." (PMID 35883700, 2022). "In contrast, TRPM7 and TRPM8 abundances are elevated in pancreatic cancer where they play roles in the amelioration of OIS and replicative senescence." (PMID 35406743, 2022). "We investigated the expression of TRPM7, TRPM6 and periostin (POSTN), a marker of activated CSPs, in pancreatic cancer samples using GEPIA tool." (PMID 35883700, 2022). "In 2010, much like TRPM7 and TRPM2, TRPM8 was reported to be overexpressed in pancreatic cancer cell lines (PANC-1 and BxPC-3) when compared to pancreatic ductal epithelia." (PMID 33925979, 2021). "We have discovered the regulatory roles of the zebrafish ortholog of mammalian TRPM7 in development of exocrine pancreas, and we subsequently identified the expression and functions TRPM7 and TRPM8 in human pancreatic cancer." (PMID 25770184, 2015). "Their identities and functional roles in have recently been discovered in pancreatic cancer; in particular, the transient receptor potential (TRP) channels TRPM7 and TRPM8." (PMID 25770184, 2015). "Additionally, down-regulation of TRPM7 in human pancreatic cancer cells inhibited proliferation by arresting the cells in the G0/G1 and G2/M phases of the cell cycle, and impaired cell migration and invasion; these effects could be reversed by Mg2+ supplementation." (PMID 25079291, 2014). "Furthermore, TRPM7 and RPSA co-localized at the plasma membrane in human pancreatic cancer cells, and this complex was proposed to regulate cell migration." (PMID 38255793, 2024). "Finally, we showed that TRPM7 channels and RPSA receptors are colocalized at the plasma membrane of human pancreatic cancer cells." (PMID 32733880, 2020). "For this reason, MIA PaCa-2 pancreatic cancer cells were pre-incubated with EGCG (10 μM) for 1 h, then incubated with or without AG-9 (10–7 M) for 24 h before fixation with paraformaldehyde and labeling with anti-TRPM7 and RPSA antibodies." (PMID 32733880, 2020). "Sub-group analysis indicates that anti-TRPM7 immunoreactivity in the primary pancreatic tumor that metastasized (n = 11) tends to be higher than that in non-metastatic pancreatic tumors (n = 266) (P = 0.06)." (PMID 25770184, 2015). "We are currently investigating the mechanisms which mediate the functional roles of TRPM7 and TRPM8 and attempting to develop these ion channels as clinical biomarkers and therapeutic targets for achieving the goal of personalized therapy in pancreatic cancer." (PMID 24278689, 2012). "The purpose of this paper is to examine the newfound roles of the transient receptor potential (TRP) ion channels, in particular the melastatin subfamily members TRPM7 and TRPM8, in pancreatic cancer and discuss their potential as clinical biomarkers and therapeutic targets." (PMID 24278689, 2012). "We speculate that TRPM7 and its regulated Mg2+ homeostasis modulate epidermal growth factor (EGF)-induced signaling pathways, resulting in cellular proliferation, survival, and migration/invasion of pancreatic cancer cells." (PMID 25770184, 2015).
neuroblastoma (22 papers, 2012 to 2024). Neuroblastoma (NB) is the most common solid, extracranial childhood tumor. "In neuroblastoma cells, the upregulation of TRPM7 was associated with increased metastatic behavior." (PMID 36142596, 2022). "This neurotoxin-mediated loss of TRPM7 expression further decreases TRPM7 activity thereby decreasing intracellular Mg2+, which leads to the loss of neuroblastoma cells." (PMID 32390858, 2020). "Our data suggest that β-AR agonist protects against neurotoxin-mediated loss of neuroblastoma cells, which was mediated through TRPM7." (PMID 32390858, 2020). "Neurotoxin treatment has been well used as a model for PD and using this in vitro model we have here established the significance of β−AR-mediated activation of TRPM7 in the loss of neuroblastoma cells." (PMID 32390858, 2020). "β-AR agonist potentiated TRPM7 function and maintained Mg2+ homeostasis that is essential for the survival of neurotoxin-induced loss of neuroblastoma SH-SY5Y cells." (PMID 32390858, 2020). "Our results further provide evidence and we show for the first time that β-AR agonists activate TRPM7, which modulate Mg2+ homeostasis that prevents neurotoxin-induced loss of neuroblastoma cells." (PMID 32390858, 2020). "Using fluorescent monitoring of intracellular Ca2+ levels we reported that in TRPM7-overexpressing mouse neuroblastoma cells (N1E-115/TRPM7), addition of PLC-activating agonists causes a sustained Ca2+ influx that is not observed in N1E-115 control cells." (PMID 30615643, 2019). "In accordance with our findings, TRPM7 inhibition also causes a reduction in invadosome formation in N1E-115 neuroblastoma cells." (PMID 25965832, 2015). "Using multiple neuroblastoma cell models, we demonstrate that TRPM7 expression closely associates with the migratory and metastatic properties of neuroblastoma cells in vitro and in vivo." (PMID 25797249, 2015). "The TRPM7 channel was implicated in Ca2+ flicker activity during migration in a neuroblastoma cell line transfected with this channel." (PMID 23620825, 2013). "In addition, high TRPM7 expression in patients with neuroblastoma has been linked to metastatic propensity Furthermore, TRPM7 expression has been linked to EMT." (PMID 35771152, 2022). "Interestingly, neurotoxin treatment did not alter the expression of β2-AR subtype; whereas loss of TRPM7 protein was observed in MPP+-treated neuroblastoma cells." (PMID 32390858, 2020). "Moreover, analysis of the TRPM7-associated interactome in neuroblastoma cells identified proteins which were mainly related to the actin cytoskeleton, such as Myosin IIA, Drebrin and the Myosin phosphatase Rho-interacting protein (p116RIP)." (PMID 33240883, 2020). "For example, TRPM7 channels are linked to high-calcium microdomains, also called calcium flickers or sparks, promoting directional migration in human lung fibroblasts and also invadosome formation in mouse neuroblastoma cells." (PMID 32733880, 2020). "Thus, increased TRPM7 expression may correlate with MYCN expression, but whether TRPM7 mRNA expression associates with disease progression in neuroblastoma patients remains to be established." (PMID 25797249, 2015). "Components of this TRPM7 interactome correlated with human neuroblastoma metastasis and disease outcome." (PMID 38255793, 2024). "It has been demonstrated that TRPM7 plays a role in other cancers, including gastrointestinal, lung, leukemia, head and neck carcinoma and neuroblastoma." (PMID 37762011, 2023). "TRPM7 has a fundamental role in the survival of dopaminergic human neuroblastoma SH-SY5Y cells, and the suppression of TRPM7 inhibits Mg content and mitochondrial function, inducing cell death." (PMID 36613667, 2022). "The downregulation of TRPM7 expression in the SH-SY5Y neuroblastoma cell line, as well as microarray and studies of bioinformatics, were performed." (PMID 36142596, 2022).
neuroblastoma (continued). "Nevertheless, in 2018, Broertjes and colleagues showed that TRPM7 Ca2+ currents in mouse neuroblastoma cells decreased when cAMP concentration increased and when the PKA catalytic domain was inhibited." (PMID 33291725, 2020). "This suggests a role for TRPM7 in aggressive phenotypes in neuroblastoma cells via p116RIP-mediated RhoA/ROCK regulation and subsequent changes in cytoskeleton dynamics." (PMID 33240883, 2020). "One of the important findings presented here was that TRPM7 is the major ion channel that modulates Mg2+ homeostasis in neuroblastoma cells." (PMID 32390858, 2020). "This has been clearly demonstrated in fibroblasts and neuroblastoma cells where re-expression of TRPM7, as well as a kinase-inactive mutant of TRPM7 on knock out cells, reverted phenotypic changes in cell polarization enhancing cell spreading and adhesion." (PMID 33132914, 2020). "In recent years, it has been reported that the expression of TRPM7 is promoted by N-Myc protein in neuroblastoma cells." (PMID 30836897, 2019). "Using the N1E-115 neuroblastoma system, we here describe that the TRPM7-mediated sustained Ca2+ influx is abrogated upon elevation of cAMP levels." (PMID 30615643, 2019). "We previously showed that in neuroblastoma cells that overexpress TRPM7 moderately, stimulation with Ca2+-mobilizing agonists leads to a characteristic sustained influx of Ca2+." (PMID 30615643, 2019). "We were able to confirm a positive association between TRPM7 and MYCN mRNA expression in two out of five additional neuroblastoma patients datasets that are publically available." (PMID 25797249, 2015). "In this study, we show that TRPM7 overexpression confers a malignant phenotype onto poorly metastatic neuroblastoma cells in vivo." (PMID 25797249, 2015). "To this end, we intravenously injected luciferase expressing neuroblastoma cells that were previously generated to either overexpress mouse TRPM7 (mTRPM7) or an empty vector control (Control), into Rag2−/−Il2rg−/− immunodeficient mice." (PMID 25797249, 2015). "Despite the up regulation of some other EMT inducers such as SOX9 and EOMES upon TRPM7 knockdown, these results suggest that TRPM7 maintains epithelial-like neuroblastoma cells in a progenitor-like migratory state." (PMID 25797249, 2015). "As MYCN was essential for proliferation of these cells, the SH-SY5Y neuroblastoma model provides a physiological relevant model to study the functional interactions between TRPM7 and MYCN in cell proliferation." (PMID 25797249, 2015). "Overall, our data indicate that TRPM7 contributes to neuroblastoma progression by maintaining progenitor-like features." (PMID 25797249, 2015). "Consistent with the large differences between neuroblastic and epithelial-like neuroblastoma cells, this set of genes showed only modest overlap with the genes that were up or down regulated by TRPM7 shRNA in SH-SY5Y cells (5.6% up, 7.1% down)." (PMID 25797249, 2015). "Using neuroblastoma cells that are made to express high levels of MYCN, experiments by Penner and colleagues suggest that TRPM7 expression is required for MYCN-enhanced proliferation of neuroblastoma cells." (PMID 25797249, 2015). "Combined with our in vitro and in vivo data, these data support the notion that shRNA-mediated knockdown of TRPM7 impairs the malignant potential of human SH-SY5Y neuroblastoma cells at the gene expression level, by reducing a progenitor-like state." (PMID 25797249, 2015). "Since metastatic neuroblastoma cells adopt the migratory potential of disseminating neural crest cells, we set out to evaluate the effects of TRPM7 expression on neuroblastoma cell migration." (PMID 25797249, 2015). "Selection of up and down regulated genes in SH-SY5Y TRPM7 shRNA cells that are known to control neural crest differentiation (Diff), migration (Migr) and/or neuroblastoma progression (NB)." (PMID 25797249, 2015).
neuroblastoma (continued). "We set out to examine the expression level of the Mg2+-influx channels TRPM6 and TRPM7 in the largest publicly available neuroblastoma expression profiling dataset, the Kocak-649 cohort." (PMID 25277194, 2014). "Over-expressing TRPM7 in a neuroblastoma cell line facilitated cell adhesion and formation of podosomes and invadosomes, and inhibiting TRPM7 reduced migration of activated T cells." (PMID 25148577, 2014). "- In mouse neuroblastoma cells (N1E-115), TRPM7 promotes formation of Ca2+ sparking and invadosome by affecting actomyosin contractility independent from Ca2+ influx." (PMID 25079291, 2014). "Genetic suppression of TRPM6/TRPM7 through siRNA inhibits cell proliferation, suggesting that N-Myc can promote neuroblastoma cell proliferation through up-regulation of divalent cation-transporting channels." (PMID 25277194, 2014). "TRPM7 can respond to membrane stretch and mediate localized Ca2+ entry at the leading edge of migrating fibroblasts and neuroblastoma cells." (PMID 25148577, 2014). "An earlier study over-expressed TRPM7 in the N1E-115 neuroblastoma cell line, and showed that it induced podosomes and was present in them." (PMID 23158496, 2012). "Podosome formation in a neuroblastoma cell line was induced by over-expressing and activating the Ca2+-permeable channel, TRPM7, and is consistent with a dependence on intracellular Ca2+." (PMID 23158496, 2012). "TRPM7, as a part of a cytoskeletal complex, has been suggested to be involved in the control of dynamic formation and the function of cell adhesions and cellular protrusions in mouse neuroblastoma cell line." (PMID 38255793, 2024). "In mouse neuroblastoma cells, TRPM7 was enriched at invadosomes (mechanosensory modules involved in cell adhesion and migration), and TRPM7 activity has been reported to regulate invadosome dynamics by affecting the tension–relaxation balance of the actomyosin cytoskeleton." (PMID 38255793, 2024). "Sun and his collaborators recently reported that apoptotic neuronal cell death induced by a Parkinson’s disease-related neurotoxin, MPP+, is protected by TRPM7 activation induced by isoproterenol and by TRPM7 overexpression in dopaminergic differentiated neuroblastoma SH-SY5Y cells." (PMID 37842082, 2023). "In neuroblastoma, another CNS tumor, TRPM7 promotes a stem-like phenotype and promotes metastasis." (PMID 37762011, 2023). "Moreover, isoproterenol-mediated activation of TRPM7 restored Mg2+ homeostasis in neuroblastoma cells." (PMID 32390858, 2020). "Finally, in 2020, Sun and colleagues demonstrated TRPM7 activation by a β-adrenergic receptor agonist like isoproterenol and its activation regulates Mg2+ homeostasis in neuroblastoma cells." (PMID 33291725, 2020). "Moreover, neurotoxins inhibited TRPM7 expression and function, but the restoration of TRPM7 expression increased neuroblastoma cell survival." (PMID 32390858, 2020). "Consistent with this notion, we show here that TRPM7 overexpression confers a metastatic phenotype onto an otherwise poorly metastatic neuroblastoma cell line, while shRNA-mediated knockdown of TRPM7 reduces the migratory properties of neuroblastoma cells." (PMID 25797249, 2015). "Indeed, we observed that TRPM7 expression is required for migration of neuroblastic (N-type) and epithelial-like (S-type) neuroblastoma cells, resembling the migratory potential of neural crest cells." (PMID 25797249, 2015). "However, based on an extensive literature search, we postulate that TRPM7 knockdown redirects neuroblastoma gene expression by reducing stemness and motility, and promoting differentiation." (PMID 25797249, 2015). "Overall, we conclude that TRPM7 drives neuroblastoma cell migration." (PMID 25797249, 2015). "Ultimately, specific TRPM7 inhibitors such as Waixenicin A, could potentially be used to induce neuroblastoma differentiation, and may prove useful in treatment of neuroblastoma in future (pre-) clinical studies." (PMID 25797249, 2015).